CFC1B (cryptic, EGF-CFC family member 1B)
Tractability: Antibody: UniProt places it where antibodies can reach, with high confidence; UniProt predicts a signal peptide or a membrane-spanning region; its Gene Ontology location is reachable by antibodies, with medium confidence.
Gene: Protein-coding gene on chromosome 2 (130,521,197 to 130,528,604, forward strand). Ensembl gene ENSG00000152093.
Subcellular location: Secreted
Gene Ontology:
Molecular function: activin receptor binding; nodal binding
Biological process: anterior/posterior pattern specification; blood vessel development; determination of left/right symmetry; heart development; nodal signaling pathway; signal transduction
Cellular component: cell surface; extracellular region
Homologues: Orthologues: chimpanzee CFC1B (99% identical), macaque CFC1 (69% identical), mouse Cfc1 (45% identical), rat Cfc1 (45% identical), tropical clawed frog tdgf1.2 (26% identical). Paralogues in human: CFC1 (99% identical), CRIPTO (22% identical), CRIPTO3 (22% identical), EGFL7 (17% identical), EGFL8 (14% identical).